MAFA (MAF bZIP transcription factor A)
Diseases named in the same sentence as MAFA in open-access papers (continued):
Sharing a sentence is not in itself a finding about the gene and the disease.
infection (7 papers, 2012 to 2023). The state of being infected such as from the introduction of a foreign agent such as serum, vaccine, antigenic substance or organism. "However, the reporter gene activity had disappeared by 14 days after the infection, indicating that the β-like cell conversion by Pdx1/NeuroD/MafA gene transfer was transient or incomplete." (PMID 23593212, 2013). "At 3days after infection, selective increases in the mRNA levels of insulin I (Ins1) and insulin II (Ins2) were observed in the cells that had been infected with a triple combination of adenovirus (Pdx1 and MafA, with either Ngn3 or NeuroD1) in a semiquantitative RT-PCR analysis." (PMID 29768476, 2018). "The Pdx1, NeuroD, and MafA genes were transferred by adenovirus vectors, and serial BLI was monitored before and after infection." (PMID 23593212, 2013). "In conclusion, our findings demonstrated that genetic manipulation producing infection by a combination of PDX-1 NeuroD1, and MafA and their subsequent expression significantly promoted insulin-producing function of mMSCs." (PMID 22761608, 2012). "Similar to WT STm infection, genes involved in the regulation of immune responses (ATF3, BATF3, ETS2, IRF9, NFκB2, MAFA, TNFAIP3), effector functions, (CCL4, CD200L, CD40, CD72, CD80, IL18) and TLR signaling, (EAF2, TLR15, TRAF3IP2, TOLLIP) were upregulated after ΔprgH STm infection in both models." (PMID 37854334, 2023). "The ratios of nGFP-positive cells at 24 hours after infection with the indicated vector at an optimal multiplicity of infection (MOI) were as follows: 94.1% ± 4.5% for pAd-Pdx1; 88.8% ± 7.6% for pAd-Ngn3; 88.6% ± 3.1% for pAd-NeuroD1; and 87.7% ± 4.2% for pAd-MafA." (PMID 29768476, 2018).
tumor (7 papers, 2013 to 2025). "Consistent with the immunohistochemistry staining of PDICs, we found that this tumor had corresponding absences of insulin and MafA expression." (PMID 23691228, 2013). "Moreover, this ubiquitination inhibits MafA transcriptional activity driven by GSK3β therefore suppressing MM cell proliferation and tumor growth." (PMID 37028761, 2023). "Notably, these alterations in tumor suppression were consistent with that the protein levels of both MafA and HERC4." (PMID 37028761, 2023). "Genes implicated in embryonic and organ development, including SHH, NEUROG3, and MAFA, were downregulated, while immune-related genes like CCL2 and HAVCR2 were upregulated, suggesting immune modulation and alterations within the tumour microenvironment." (PMID 40683913, 2025). "Two significant pathways, hsa04080, Neuroactive ligand-receptor interaction, and hsa04950, Maturity onset diabetes of the young (MODoY; with transcription factors FOXA3, NKX6-1, MAFA, PAX6, PDX1), were identified for the genes expressed more highly in the high-CCNE1 tumours." (PMID 38612869, 2024).
cancer (4 papers, 2021 to 2025). A tumor composed of atypical neoplastic, often pleomorphic cells that invade other tissues. "MAFA is one of the large Maf proteins that have been implicated in carcinogenesis, as demonstrated in cell culture, animal models, and cancer tissues." (PMID 34573430, 2021). "The MAFA gene, identified as harbouring a disruptive in-frame deletion in the seven considered patients, is known to be involved in oncogenic activities and cancer progression." (PMID 34573430, 2021). "MAFA, MAFB, and MAF are large MAF proteins that have been shown to be oncogenes in tissue cultures, animal models, and human cancer." (PMID 35406570, 2022).
cardiac diseases (1 paper, 2020). "Interestingly, except for MAFA that is involved in insulin secretion, all 7 gene products were found to be implicated in both pulmonary and cardiac diseases." (PMID 33308225, 2020).
metabolic disease (1 paper, 2022). A congenital disorder (due to inherited enzyme abnormality) or acquired (due to failure of a metabolically important organ) disorder resulting from an abnormal metabolic process. "In the context of metabolic disease, disruption of MafA–Kat2b interaction results in the loss of β-cell maturity." (PMID 35454124, 2022).
MAFA also shares sentences with these, for which no sentence is quoted: Hyperinsulinemia (2 papers); Impaired glucose tolerance (2); viral infection (2); diabetic nephropathy (1); Hypoinsulinemia (1); leiomyosarcoma (1); metabolic syndrome (1); periodontitis (1).